FOXE1 (forkhead box E1)
Diseases named in the same sentence as FOXE1 in open-access papers (continued):
Sharing a sentence is not in itself a finding about the gene and the disease.
tumor (continued). "The FOXE1 and ITGA3 expression and protein levels were negatively associated with miR‐524‐5p expression in PTC cell lines, patients' tumor and papa‐cancer tissues." (PMID 30941771, 2019). "Germline FOXE1 and AXIN1 variants might have a role in thyroid ectopy and cleft palate, which, together with MAPK pathway activation, may contribute to tumours’ malignant transformation." (PMID 38396644, 2024). "Combined data from gene expression, polymorphisms, enhancer regions, and methylation have suggested that FOXE1 could be a novel tumor suppressor." (PMID 39588344, 2024). "However, another report detected an increase of FOXE1 expression in PTC tumor tissues that correlated with a worse clinical prognosis." (PMID 39588344, 2024). "Consistent with the results of FOXE1 inhibition of tumor cell proliferation in vitro, FOXE1 transfection could significantly inhibit the tumorigenesis of DLD-1 cells in vivo." (PMID 38734646, 2024). "FOXE1 staining was negative in all tumour samples, regardless of the FOXE1 mutation status of the patient." (PMID 38396644, 2024). "Ectopic expression of FOXE1 could suppress tumor cell growth and migration and affect the organization of the actin cytoskeleton together with suppressing tumorigenicity in vivo." (PMID 38734646, 2024). "The expression of two additional M2-related markers, ARGINASE1 (ARG) and INTERLEUKINE10 (IL10), was measured to further evaluate if the reduction of FOXE1 levels could affect the abundance of this macrophage subpopulation within the tumour." (PMID 34299284, 2021). "Furthermore, FOXE1 expression is decreased in tumor tissues and TC cell lines; and FOXE1 overexpression partially rescued the effects of miR-330-5p on cell proliferation, migration, and invasion in TPC-1 and K-1 cells." (PMID 34306074, 2021). "Consistently, we also observed a reduction of CAFs in BRAF FOXE1+/- tumour stroma." (PMID 34299284, 2021). "Furthermore, the xenotransplant experiment showed that enforced FOXE1 expression significantly decreased the tumor-forming capacity of HCT116 cells." (PMID 31918722, 2020). "Collectively, our results established FOXE1 as a critical tumor suppressor, regulating CRC cell growth and aerobic glycolysis through FOXE1/HK2 axis, which therefore could be a promising therapeutic target for CRC." (PMID 31918722, 2020). "Thus, by deregulation of FOXE1, it is likely that this protein can become a tumor suppressor or an oncogene through the Wnt pathway, either dependently or independently of β-catenin." (PMID 28928994, 2017). "In spite of this, FoxE1 expression levels seem to be unaltered in human tumours." (PMID 23675434, 2013). "Finally, we investigated whether FOXE1 expression had a suppressive effect on tumor cell growth in vivo." (PMID 38734646, 2024). "The results suggested that FOXE1 could prevent the recombination of F-actin and significantly reduce the number of stress fibers, which may be a reason why FOXE1 weakens the migration ability of tumor cells." (PMID 38734646, 2024). "After imbuing tumor cells with silenced or reduced expression of FOXE1 using demethylation reagent 5-AZA and histone deacetylase inhibitor TSA, we found that FOXE1 expression could be restored, indicating that FOXE1 methylation is the main cause of FOXE1 gene-silencing." (PMID 38734646, 2024). "However, FOXE1 gene-promoter hypermethylation was confirmed in these tumor cell lines." (PMID 38734646, 2024). "We also detected the age-related effect of rs1867277 (FOXE1) conferring the higher risk for PTC in patients older than 55 years and the association of rs7267944 (DHX35) with PTC risk in males and that of rs6983267 (POU5F1B/CCAT2) with more advanced tumor pT stage." (PMID 33551988, 2020).
tumor (continued). "We found that FOXE1 was frequently methylated and silenced in CRC cell lines and was downregulated in CRC tissues compared with paired adjacent non-tumor tissues." (PMID 38734646, 2024). "Among the most overexpressed genes in tumor cells compared to normal tissue were the transcription factors HOXB9, SIM2, ZIC5, SP8, TFAP2A, FOXE1, HOXB13, and SALL4; the cancer testis antigen CT83; and the cytokine IL23A." (PMID 37228492, 2023). "By contrast, the expression levels of FOXE1 in PTC and normal thyroid tissue were very similar (normal tissue n = 59, tumor samples n = 501)." (PMID 31846430, 2020). "In this study, FOXE1 prohibited the proliferation of CRC cells, providing new evidence for its role as a tumor suppressor in cancer development and progression." (PMID 31918722, 2020). "Genes that were downregulated and hypermethylated in ADCs were squamous markers such as DSC3 and KRT5, as well as transcription factors such as FOXE1 and TP73, whose isoforms have demonstrated both tumor suppressor and oncogenic properties." (PMID 28787442, 2017). "In conclusion, our results suggest that the silencing or downregulation of FOXE1 in CRC is mainly regulated by methylation of the promoter region, and FOXE1 may play a role as a tumor suppressor gene." (PMID 38734646, 2024). "Nevertheless, in this case, the FOXE1 germline variant and co-occurring AXIN1 inactivation did not appear to be sufficient for tumour initiation." (PMID 38396644, 2024). "In addition to the identified FOXE1 germline variants, we performed next-generation sequencing (NGS) of the F1 and F2 probands’ leukocyte and tumour nucleic acids to investigate whether additional molecular alterations could be involved in the initiation/progression of these patients’ tumours." (PMID 38396644, 2024). "Among the most overexpressed genes in tumor cells compared to normal tissue are genes coding for transcription factors (HOXB9, SIM2, ZIC5, SP8, TFAP2A, FOXE1, HOXB13, and SALL4), cancer testis antigens (CT83), and cytokines activating regulatory Th17 cells (IL23A)." (PMID 37228492, 2023). "Subsequently, new studies showed a tumor suppressor effect of FOXE1 and demonstrated that rs1867277 is involved in differential recruitment of USF1/ USF2 transcription factors, which interferes with FOXE1 expression." (PMID 33218058, 2020). "Although FOXE1 did not promote the apoptosis of tumor cells, it may inhibit the growth of tumor cells by arresting the cell cycle." (PMID 38734646, 2024). "Even so, the involvement of methylation in FOXE expression was corroborated in TCGA data, which showed a significant negative correlation between methylation and FOXE1 mRNA expression among all the samples (tumor and non-tumor) and in the tumor samples but not in the non-tumor samples." (PMID 39588344, 2024). "Indeed, it is important to note that SW1736 cells show high levels of PAX8, FOXE1 and CDH1, compared to KTC2, indicating ATC tumor heterogeneity that may influence the response to EZH2 modulation." (PMID 37175580, 2023). "Thus, the PTC tumor cell viability was controlled by miR‐524‐5p, ITGA3, and FOXE1." (PMID 30941771, 2019). "An additional 17 downregulated genes are unique to GSC lines, including FOXE1, a developmental transcription factor whose promoter and adjacent enhancer are specifically targeted for DNA hypermethylation in GSC lines (but not bulk tumor based on comparisons with TCGA data)." (PMID 29587824, 2018).
cancer (25 papers, 2009 to 2026). A tumor composed of atypical neoplastic, often pleomorphic cells that invade other tissues. "Most of cancer-associated FOXE1 polymorphisms are likely to regulate the gene’s expression, as the polymorphisms fall in locus regulatory regions." (PMID 34299284, 2021). "Beyond genomic variants, different FOXE1 expression levels have been associated with several clinical and pathological cancer parameters, such as extra-capsular invasion, lymph node metastasis, and staging." (PMID 33375029, 2020). "Several cancer-associated polymorphisms fall into gene regulatory regions and are likely to affect FOXE1 expression levels." (PMID 33375029, 2020). "The information about the association of the FOXE1 SNP rs1867277 with TC appears to vary with ethnicity and cancer type." (PMID 28928994, 2017). "Improving knowledge of the regulatory functions of FoxE1 is necessary to clarify its role in endocrine syndromes and cancer susceptibility." (PMID 23675434, 2013). "Recently, FOXE1 has been implicated in numerous types of cancer, including PTC." (PMID 31247975, 2019). "Whereas the association with HERVH-CALB1 expression extended to other cancer types for some transcription factors (SOX2, SOX21), for others (TP63, FOXE1), it was specific to LUSC." (PMID 37192000, 2023). "The expression levels of FAIM2, NPY, and FOXE1 were also compared in the cancer samples with normal samples in validation cohort 3 and a negative relationship between methylation and gene expression was observed." (PMID 36329447, 2022). "FOXE1 is annotated as a thyroid-specific transcription factor with putative roles in thyroid development and cancer." (PMID 35119359, 2022). "BRAF FOXE1+/- cancers showed a weaker expression of both M2 markers with respect to the BRAF FOXE1+/+ ones." (PMID 34299284, 2021). "Both markers show reduced staining in the BRAF FOXE1+/- cancer samples with respect to the BRAF FOXE1+/+ ones." (PMID 34299284, 2021). "As FOXE1 induces thyroid cell motility both in development and in cancer, we analysed the migratory behaviour of FC." (PMID 34299284, 2021). "Differentiation of BRAF FOXE1+/+ and BRAF FOXE1+/− cancers was analyzed by IHC for two representative differentiated thyroid markers, the transcription factor PAX8, and the precursor of thyroid hormones thyroglobulin (TG)." (PMID 33375029, 2020). "Conversely, FOXE1+/− cancers show a weaker staining for both PAX8 and TG, with the positive cells surrounding and partially filling the follicle-like structures." (PMID 33375029, 2020). "To further characterize the differentiation state of BRAF FOXE1+/+ and BRAF FOXE1+/− cancers, we analyzed the expression of a panel of thyroid differentiation markers by quantitative RT-PCR." (PMID 33375029, 2020). "BRAF FOXE1+/− cancers show increased apoptosis, as measured by cleaved caspase-3 positive cells number." (PMID 33375029, 2020). "Recently, its expression was found to be significantly lower in cancer tissues than in paired normal tissues and silencing of FOXE1 contributed to poor prognosis for CRC patients." (PMID 31918722, 2020). "Such cancers, however, appear severely undifferentiated, indicating that FOXE1 levels affect thyroid differentiation during neoplastic transformation." (PMID 33375029, 2020). "FOXE1 is highly expressed in normal colon tissues compared with cancer tissues and low expression of FOXE1 is significantly associated with poor prognosis of CRC patients." (PMID 31918722, 2020). "FOXE1 is one of the important tumor suppressor genes, and its relationship with malignant tumors has been explored for a long time." (PMID 29788924, 2018). "ETV5 is an oncogenic member of the ETS transcription factor family, associated with cell proliferation and metastasis in various cancers, and a known target of thyroid-specific transcription factor FOXE1." (PMID 24138990, 2013). "Cancer-specific FOXE1 hypermethylation events have been identified in several cancers." (PMID 38734646, 2024).
cancer (continued). "Overall, the landscape emerging from the literature strongly indicates that either due to genetic variants or to other still unidentified regulators, the expression level of FOXE1 is a possible determinant underlying the susceptibility to PTC and/or other cancer phenotypes." (PMID 38396644, 2024). "Low FOXE1 expression in parallel with promoter hypermethylation was observed in colorectal, salivary gland, skin, and other types of cancer, and it was proposed that methylation of FOXE1 could be a promising marker for cancer detection." (PMID 39588344, 2024). "Furthermore, TG staining revealed that the differentiated cells retain thyroglobulin in the cytoplasm in both FOXE1+/+ and FOXE1+/− cancers." (PMID 33375029, 2020). "Indeed, the reduced proliferation index and increased apoptosis suggest that FOXE1+/− cancers display a less malignant phenotype." (PMID 33375029, 2020). "The analysis revealed that in BRAF FOXE1+/− cancers, the decrease of all the analyzed thyroid differentiation markers is significantly more pronounced than that observed in BRAF FOXE1+/+ ones, showing that lower FOXE1 levels are associated with less differentiated tumors." (PMID 33375029, 2020). "The different cancer histology was associated with a marked reduction of cell proliferation of BRAF FOXE1+/− cancers, as determined by immunohistochemistry (IHC) for Ki-67, compared to BRAF FOXE1+/+." (PMID 33375029, 2020). "Here, we describe the effects of FOXE1 gene dosage reduction on cancer phenotype in vivo." (PMID 33375029, 2020). "The role of FOXE1 in adult thyroid, and in particular regarding cancer risk, has not been well established." (PMID 27852061, 2016). "In addition to genetic factors, epigenetics may also explain the lower FOXE1 expression in PTC tissues, as the hypermethylation of the FOXE1 promoter has been observed in other cancers, showing an inverse correlation with its expression." (PMID 38396644, 2024). "Thus, the crosstalk between CAFs and M2 macrophages and their synergistic effect on cancer progression could be impaired in FOXE1+/- cancers." (PMID 34299284, 2021). "When cancer was induced, reduced expression of the identified chemokines was observed in FOXE1+/-, thus showing that these genes are under FOXE1 control, being both upregulated in vitro by FOXE1 ectopic expression and downregulated in vivo by FOXE1 hemizygosity." (PMID 34299284, 2021). "Functionally, IGF2BP2 promotes proliferation, suppresses thyroid differentiation genes (TSHR, SLC26A4, SLC5A5, TPO, PAX8, FOXE1, and NKX2.1), and enhances cancer stemness." (PMID 41522349, 2026). "Although expressions of 9 hyper-methylated genes were significantly different across cancer stages in the TCGA cohort, reduced expressions with increased cancer severity were observed for 3 hyper-methylated genes- SLITRK3, FOXE1, and TWIST1." (PMID 36329447, 2022). "For the remaining gDMs (NPY, FOXE1, FAIM2, and KCNA6), we found hyper-methylation in PDAC, as confirmed by the higher extent of methylation in cancer samples." (PMID 36329447, 2022). "It has already been shown, in the same cancer model, that targeting CLC2 and CSF1 impairs TAMs recruitment and M2 polarisation, as we here obtained by targeting FOXE1 as well." (PMID 34299284, 2021). "Specifically, BRAF FOXE1+/+ thyroid tissue displays a dramatic loss of the normal follicular structure, featuring a solid growth pattern as expected for this cancer model, while BRAF FOXE1+/− glands show empty structures, resembling residual follicle lumens." (PMID 33375029, 2020). "RT‐qPCR was utilized to detect the expression pattern of MATN2, FOXE1, and ITGA3 in PTC and papa‐cancer tissues." (PMID 30941771, 2019). "The FOXE1 and ITGA3 were significantly raised to 2.5 and three times in PTC comparing to papa‐cancer tissues." (PMID 30941771, 2019).
cancer (continued). "Further, AIWrap identified six new genes (VCX3A, CALHM5, ZMYND10, FOXE1, PLAT, FADD) which could be related to smoking in cancer patients, thus providing an opportunity for identifying previously unknown biological functions." (PMID 37853338, 2023). "FOXE1, TWIST1 and other hyper-methylated genes involved in cell cycle regulation were observed in PDAC cancers, thus suggesting that their down-regulation may encourage uncontrolled cell proliferation in PDAC." (PMID 36329447, 2022). "The key cancer-related genes affected by HPV integrants are Diaphanous-related formin 2 (DIAPH2) gene rearrangements and Tumour protein 63 (TP63) gene promoter aberration and Proviral integration site for Moloney murine leukaemia virus 1 (PIM1) and Forkhead box E1 (FOXE1) gene amplification." (PMID 38643337, 2024).
adenocarcinoma (2 papers, 2010 to 2024). A common cancer characterized by the presence of malignant glandular cells. "In our model, Sox2 overexpression in Scgb1a1-positive cells drives development of histologically well differentiated adenocarcinoma with significant squamous cell features including widespread expression of p63, FoxE1 and Desmoglein3." (PMID 20548776, 2010).
FOXE1 also shares sentences with these, for which no sentence is quoted: autoimmune disease (2 papers); Blepharophimosis (2); Graves disease (2); Hashimoto thyroiditis (2); leukemia (2); Obesity (2); Primary hypothyroidism (2); thyrotoxicosis (2); alopecia (1); autoimmune thyroid disease (1); Autoimmunity (1); basal cell carcinoma (1); bladder cancer (1); brain-lung-thyroid syndrome (1); cutaneous squamous cell carcinoma (1); dental caries (1); ectopic thyroid (1); endocrine disorders (1); Epicanthus inversus (1); follicular thyroid carcinoma (1); head and neck cancer (1); intellectual disability with language impairment (1); language disorder (1); medullary thyroid cancer (1); melanoma (1); microcephaly (1); myopia (1); Nail dystrophy (1); nodular goiter (1); nonmedullary thyroid cancer (1).
A further 12 diseases each share a sentence with FOXE1 in 1 paper.